SESN2 (sestrin 2)
Diseases named in the same sentence as SESN2 in open-access papers (continued):
Sharing a sentence is not in itself a finding about the gene and the disease.
neurological diseases (2 papers, 2020 to 2022). "Although the association between SESN2 and several other neurological diseases has been investigated in various studies, there are no data related to the connection between SESN2 and MS." (PMID 35195231, 2022).
respiratory diseases (2 papers, 2023). "Evidence suggests that Sesn2 is involved in oxidative-stress-related respiratory diseases." (PMID 37298433, 2023).
brain disease (1 paper, 2020). "In the current study, AAV2 (an efficient delivery system for brain disease gene therapy 33) was utilized to regulate SESN2 expression in mouse hippocampi." (PMID 32363721, 2020).
ischaemic heart disease (1 paper, 2021). "Similar reports suggested that SESN2 exerts heart‐protective effects in ischaemic heart disease." (PMID 33942488, 2021).
SESN2 also shares sentences with these, for which no sentence is quoted: Glucose intolerance (4 papers); squamous cell carcinoma (4); Myocardial fibrosis (3); non-small cell lung carcinoma (3); obstructive sleep apnea (3); type 2 diabetes (3); Alzheimer disease (2); Cerebral ischemia (2); chronic obstructive pulmonary disease (2); colon adenocarcinoma (2); Encephalopathy (2); fibrosis (2); muscular atrophy (2); cerebral infarction (1); chronic lymphocytic leukemia (1); crescentic glomerulonephritis (1); endometrial adenocarcinoma (1); endometrial polyp (1); endotoxemia (1); enterocolitis (1); Gestational Diabetes Mellitus (1); hearing loss (1); idiopathic pulmonary fibrosis (1); infarct (1); injury (1); lymphoma (1); multiple sclerosis (1); myeloproliferative neoplasm (1); nasopharyngeal carcinoma (1); oligoastrocytoma (1).
A further 14 diseases each share a sentence with SESN2 in 1 paper.